C2orf76 (chromosome 2 open reading frame 76)
Synonyms: MGC104437; LOC130355; AIM29
Tractability: PROTAC: ubiquitination databases record sites on it; its protein half-life has been measured.
Gene: Protein-coding gene on chromosome 2 (119,299,439 to 119,366,860, reverse strand). Ensembl gene ENSG00000186132.
Subcellular location (Human Protein Atlas): Endoplasmic reticulum
Gene Ontology:
Molecular function: protein binding
Genetic constraint (gnomAD): Loss-of-function variants: 9 observed, 6.91 expected, observed/expected ratio (o/e) 1.3, 90% interval 0.77 to 1.89. That is too few expected variants to judge how well the gene tolerates losing a copy. Missense variants: 85 observed, 89.12 expected, observed/expected ratio (o/e) 0.95, 90% interval 0.8 to 1.14. Synonymous variants: 31 observed, 31.74 expected, observed/expected ratio (o/e) 0.98, 90% interval 0.73 to 1.32.
Homologues: Orthologues: chimpanzee C2orf76 (98% identical), guinea pig C2orf76 (95% identical), pig C2orf76 (90% identical), dog C2orf76 (89% identical), mouse 3110009E18Rik (83% identical), macaque C12H2orf76 (77% identical), rat C13h2orf76 (67% identical), zebrafish C9H2orf76 (63% identical), tropical clawed frog c9h2orf76 (57% identical).
Diseases named in the same sentence as C2orf76 in open-access papers:
C2orf76 is named in the same sentence as 1 disease in open-access papers, as found by Europe PMC text mining. Sharing a sentence is not in itself a finding about the gene and the disease. The quoted sentences say what the papers report.
pancreatic cancer (1 paper, 2023). "Protein C2orf76 is described as a dimeric protein that is involved in the formation of an aggressive pancreatic cancer phenotype through induction of cell invasion and proliferation." (PMID 37373333, 2023).